CDC6 (cell division cycle 6)
Diseases named in the same sentence as CDC6 in open-access papers (continued):
Sharing a sentence is not in itself a finding about the gene and the disease.
cancer (continued). "CDC6 and CDT1, for instance, positively correlated with various cycle- and proliferation-related pathways, such as E2F targets and G2M checkpoint, indicating that they regulate cancer development by activating these pathways." (PMID 38728235, 2024). "To explore the impact of CDC6 expression on the tumor microenvironment in SKCM, we investigated its significant correlations with 28 types of tumor-infiltrating lymphocytes (TILs) across various human heterogeneous cancers." (PMID 39052109, 2024). "The lncRNA’s regulation of CDC6 has also been reported (such as lncrNa-CDC6); however, we found that it was mainly concentrated in cancer-related studies, and no relevant report was found in adipocyte development." (PMID 36835645, 2023). "Recent studies have elucidated that CDC6 could promote mitotic slippage by inhibiting CDK1; thus, cancer cells avoid apoptosis and exhibit PTX resistance." (PMID 35173548, 2022). "MT2A and TRIM31 which were engaged in IFN-γ signaling, CDC6, SGK1 and PTP4A1 genes, presented a homogeneous expression pattern in both test and Validation datasets, although our results were contradictory to other studies in different cancers." (PMID 34249670, 2021). "The proliferation of radioresistant cancer cells was retarded, more radioresistant CNE2-R cells are arrested in G0/G1 phase, suggesting that DNA replication initiation probably has been blocked, and CDC6 is an essential molecule for DNA replication initiation." (PMID 30158672, 2019). "Our results may affect the understanding of the process of cancerogenesis since CDC6 and its interactions with CDK1 play an important role in mitotic regulation and in cancer etiology." (PMID 31795221, 2019). "Several synthetic lethality screens have been performed on KRAS mutant cancer cell lines to determine potential targets, and results have frequently included genes important in cell cycle progression or mitosis, such as CDK1, cyclin A2, PLK1, and CDC6." (PMID 27167191, 2016). "miR-1297 could exert cancer-suppressing role in GC, in part, by downregulating CREB1 or CDC6." (PMID 34821362, 2021). "Since the combination of CDC6 depletion and IR could not induce the apoptosis of all radioresistant cancer cells, we tested cell senescence when CDC6 was depleted alone or in combination with IR in CNE2-R cells by β-galactosidase assay." (PMID 30158672, 2019). "Since mTOR signaling is upregulated in most cancers, the negative control of miR-3178 by mTOR signaling suggests that miR-3178 may be a novel tumor suppressor by targeting CDC6." (PMID 31285446, 2019). "Considering that Cdc6 is normally absent in quiescent and differentiated cells, it could be specific markers for cancer cells." (PMID 27246979, 2016). "Consistent with findings in OTUD6A knockdown cancer cells, overexpression of OTUD6A increased the protein level but not the mRNA level of CDC6 in UMUC3 and 786-O cells." (PMID 38685067, 2024). "Similar to the effect of the ubiquitination-resistant mutant of Geminin, expression of cancer-derived SPOP mutants also increased Cdt1 binding to MCM2, CDC6, and ORC2 but had no influence on Geminin binding to Cdt1." (PMID 34599168, 2021). "Indeed, Cdc6 expression was significantly correlated with survival in patients whose cancer expressed three or fewer MCM2-7 genes at a high level (Wilcoxon-Gehan test, p = 0.004), but not in those patients whose cancer expressed four or more MCM2-7 genes at high level (p = 0.425)." (PMID 28428557, 2017).
tumor (88 papers, 2004 to 2026). "IHC analysis of the tumor specimens revealed increased immune cell infiltration coupled with reduced proliferative indices in CDC6‐deficient tumors." (PMID 39739618, 2025). "Consistent with the observation from in vitro experiments, overexpression of CDC6 rescued the increased chemosensitivity caused by OTUD6A knockdown in gemcitabine-treated T24 tumours." (PMID 38685067, 2024). "Notable associations were observed between CDC6 expression and the tumor mutational burden (TMB) and microsatellite instability (MSI), as well as immune cell infiltration." (PMID 39684684, 2024). "ZNF143 positively regulates tumor growth through transcriptional regulation of DNA replication and cell-cycle-associated genes (such as CDC6, PLK1, and MCMs) in multiple solid tumors, including in LCs." (PMID 34616428, 2021). "In general, elevated expression of CDC6 mRNA was associated with increased CHEK1 mRNA expression in the tumour samples compared to normal tissue from the same site." (PMID 27775084, 2016). "Specifically, the inhibition of DBF4, CCNA2, CCNB1, MCM6, CDC45, CHEK1, and CDC6 may be implicated in KCNQ1-mediated tumor suppression." (PMID 35216393, 2022). "Indeed, Cdc6 overexpression has been found to be a feature in certain tumours and has been associated as an early event in malignancies." (PMID 32010971, 2020). "Our results indicate that the overexpression of CDC6 is associated with increased tumor grade." (PMID 26317630, 2015). "CDC6 expression was associated with tumor size, lymph node metastasis, and disease stage, indicating that CDC6 may promote the proliferation and invasion of tumor cells and serves as a novel ESCC therapeutic target." (PMID 38519533, 2024). "Results confirmed that CDC6‐overexpressing tumor cells exhibited significantly elevated TGF‐β1 levels both intracellularly and in the coculture medium, which was further validated by ELISA." (PMID 39739618, 2025). "Analysis of the Human Protein Atlas (HPA) datasets through IHC also indicated increased protein expression levels of CDC6 in tumor samples of the kidney, liver, pancreas, and skin." (PMID 39739618, 2025). "In our study, we highlight the pivotal role of tumor cell‐derived CDC6 in driving fibroblast senescence via TGF‐β1 secretion and oxidative stress." (PMID 39739618, 2025). "It was noted the RORC was significantly downregulated in tumor tissues compared to the normal tissue, while CDC6 was upregulated." (PMID 40356904, 2025). "To investigate the functional relationship between CDC6 and fibroblast senescence, we established a tumor cell‐fibroblast coculture system." (PMID 39739618, 2025). "For CDC6, evidence has been accumulated that it acts as an oncogene promoting tumour progression and as a potential driver of tumourigenesis." (PMID 38728235, 2024). "Taken together, these data demonstrated that OTUD6A promotes CDC6-ATR-Chk1 signalling pathway activity to confer chemoresistance on tumour cells." (PMID 38685067, 2024). "Patients bearing BCa tumours with relatively high levels of OTUD6A or CDC6 showed poorer overall survival (OS) outcomes." (PMID 38685067, 2024). "CDC6 is a true proto-oncogene involved in tumor initiation and progression and is overexpressed in many tumor types." (PMID 39684684, 2024). "The correlation between the expression of CDC6 and immune cell markers indicated that it plays an important role in the regulation of tumor immunity." (PMID 39684684, 2024). "We further characterized the pivotal role of OTUD6A in tumour progression and chemoresistance via upregulation of CDC6." (PMID 38685067, 2024). "Results significantly confirmed higher gene expression of ORC1 and CDC6 in tumor cells compared to normal cells." (PMID 37945594, 2023). "Previous studies have shown that CDC6 is a bona fide proto-oncogene that involves in tumor initiation and progression, and it is often over-expressed in many tumor types, providing the rationales for CDC6 as a novel therapeutic target." (PMID 37833632, 2023).
tumor (continued). "As an oncogene, CDC6 is highly expressed in tumor tissues, driving tumor cell DNA replication and unlimited proliferation." (PMID 37240065, 2023). "Initially, we investigated the oncogenic function of LINC01088 and CDC6 and the tumor-suppressing role of miR-22 in PCa." (PMID 37501932, 2023). "Our study found six genes (PCNA, CDC6, CDC7, CDT1, CDK2, and RBBP8) that were most significantly linked with expression levels of key genes and tumor progression." (PMID 37656243, 2023). "A study has confirmed that the expression level of CDC6 is significantly elevated in NSCLC tumor tissues." (PMID 36232605, 2022). "CDC6 promotes the response of the G2/M checkpoint and is positively correlated with tumor progression." (PMID 35875060, 2022). "Decreased CDC6 expression in tumor cells effectively inhibits tumor cell growth and promotes apoptosis by preventing G1/S and S/G2 transition." (PMID 35875060, 2022). "Many research has shown that CDC6 has the characteristics of oncogenes, and it also plays a significant role in assessing tumor grade and predicting prognosis." (PMID 34136398, 2021). "Compared with CDC6 expression level in normal renal tissues, we found that CDC6 expression in tumor tissues was elevated." (PMID 34136398, 2021). "Surprisingly, we found CDC2 and CDC6 expression was significantly increased in human HCC samples compared with non‐tumour tissue." (PMID 33951279, 2021). "The results showed that CDC6 expression was closely related to age (P = 0.012), tumor size (P = 0.011), T stage (P = 0.041) and Fuhrman grade (P = 0.008)." (PMID 34136398, 2021). "The mRNA expression level of CDC6 was investigated to identify the differential expression pattern between tumor tissues and normal tissues from TCGA." (PMID 34136398, 2021). "CDC6 expression was closely related to some prognostic parameters, including age, tumor size, T stage, and Fuhrman grade, in tissue obtained from 118 patients." (PMID 34676165, 2021). "There were significantly correlations with CDC6 and immune cell infiltration levels and tumor microenvironment." (PMID 34136398, 2021). "The high expression of CDC6 is positively correlated with Fuhrman grade and tumor T stage, which strongly indicates that CDC6 plays a vital role in the occurrence and development of ccRCC." (PMID 34136398, 2021). "Given their high biosafety, PAR‐Lipos are used to mediate the knockout of the oncogene CDC6 in vivo, which results in significant tumor growth inhibition." (PMID 32714743, 2020). "Significant difference of the RNA expression between the T lymphocyte from health individuals and HCT116 (data unpublished) was observed, which supports our result that cdc6 expression in tumor cell is higher than that in normal cells." (PMID 32249466, 2020). "We observed that the expression of cdc6 in both tumor cells and cell mixture are extremely higher than that in PBMCs from cord blood or health individuals, and cdc6 expression in PBMCs from cord blood is lower than that from health individuals." (PMID 32249466, 2020). "We first detected the expression of cdc6 in peripheral blood mononuclear cells (PBMCs) and tumor cells by in situ hybridization with cdc6 RNA probe." (PMID 32249466, 2020). "Given their high biosafety, PAR‐Lipos were used to mediate knockout of the oncogene CDC6 in vivo, which resulted in significant tumor growth inhibition." (PMID 32714743, 2020). "For cdc6 gene expression, any samples from tumor cells, mix samples or PBMCs from cord blood with a 2−ΔΔCt>2 or < 0.5 was considered significantly different from health control." (PMID 32249466, 2020). "For the roles of immune and inflammatory response, the correlation between CDC6 expression and the marker sets of immune cells indicated CDC6 played an important role in regulating tumor immunology." (PMID 33173413, 2020).
tumor (continued). "When compared the cdc6 expression in cells from difference sources, we found that A549 tumor cell line had the strongest expression of cdc6, samples from cord blood showed the least expression level, indicating the detection strategy of RT‐qPCR is reasonable." (PMID 32249466, 2020). "Results from in situ hybridization experiments suggest that cdc6 expression in A549 tumor cells was stronger obviously than in peripheral blood mononuclear cells." (PMID 32249466, 2020). "The residual tumor xenografts were harvested, and CDC6 protein expression in the individual tumor specimens was assessed by western blot." (PMID 30158672, 2019). "We compared CDC6 and Ki67 protein levels in tumor tissues from NPC patients by immunohistochemistry." (PMID 30158672, 2019). "The results showed that CDC6 is positively correlated with tumor progression, and CDC6 level is much higher in the IR/chemo-treated tumors with high progression." (PMID 30158672, 2019). "Though CDC6 has been reported to be involved in tumor transformation, cell apoptosis, senescence, and EMT, the full role of CDC6 in radiosensitivity remains to be determined." (PMID 30158672, 2019). "Consistent for the two cell lines, CDC6 knockdown or IR exposure alone inhibited the growth of tumor xenografts, and CDC6 depletion significantly improved IR-repressed tumor growth until 32 days after treatment." (PMID 30158672, 2019). "The combination of CDC6 depletion and IR significantly elevated p16 levels in the tumor xenografts, which indicated that the combination of CDC6 depletion and IR significantly promoted cell senescence." (PMID 30158672, 2019). "Consistent for the two cell lines, CDC6 knockdown or IR exposure alone inhibited the growth of tumor xenografts, and CDC6 depletion significantly improved IR-repressed tumor growth until 32 days or 48 days after treatment." (PMID 30158672, 2019). "CDC6 expression remarkably decreased in the tumor xenografts expressing CDC6 shRNA induced by tetracycline." (PMID 30158672, 2019). "Higher CDC6 expression has been validated in NPC tumor tissues that partially responded to IR (PR, resistant) than completely responded to IR (CR, sensitive)." (PMID 30158672, 2019). "We suggest that Cdc6 overexpression in human tumours requires a concomitant increase in Chk1 to counterbalance the deleterious effects of origin hyperactivation-induced DNA damage." (PMID 27775084, 2016). "Fold changes in CDC6 or CHEK1 mRNA expression in human tumours compared to normal tissue controls were determined using the Firehose analysis tool from the Broad Institute TCGA Genome Data Analysis Center." (PMID 27775084, 2016). "Adapting the tumour cell growth environment from an anchorage-dependent to -independent one resulted in decreased Chk1 protein expression as well as decreased Cdc6, CDT1 and RRM2 protein expression." (PMID 27775084, 2016). "The relative expression of the genes Bmi-1, CCND1, and CDC6 was significantly increased in samples from all the tumor grades analyzed, and grade IV tumors were the most frequent." (PMID 26317630, 2015). "To provide more evidences to support the skin transformation phenotype, we performed plastic section through the tumor-like tissue in the pectoral fin of cdc6/c-myc transgenics." (PMID 25051368, 2014). "To examine the transformation phenotype in zebrafish skin, we performed plastic section through the tumor-like structure in the anal fin area of cdc6/c-myc transgenics." (PMID 25051368, 2014). "Intriguingly, co-overexpression of cdc6 and c-myc in transgenic zebrafish skin triggered tumor-like transformation, apoptosis attenuation, genomic instability, and EMT, hallmarks of malignant tumorigenesis." (PMID 25051368, 2014). "Next we found that co-overexpression of cdc6 and c-myc induces tumor-like transformation in zebrafish skin." (PMID 25051368, 2014).
tumor (continued). "Western blotting analysis of tumor lysates showed that H69 tumors isolated from capsaicin treated mice had lower levels of cyclin E, TS, cdc25A and cdc6, as compared to control untreated mice." (PMID 20421925, 2010). "Our results showed that the tumor with higher CDC6 and CDT1 expression revealed more aggressive behavior." (PMID 19116018, 2008). "Subcutaneous xenograft mouse models were established to evaluate the impact of CDC6 on tumor growth in vivo, while mechanistic investigations were carried out using co-immunoprecipitation, chromatin immunoprecipitation, dual-luciferase reporter assays, and nucleocytoplasmic fractionation." (PMID 42014675, 2026). "Notably, CDC6‐deficient tumors exhibited markedly enhanced sensitivity to anti‐PD1 therapy, as evidenced by superior tumor regression." (PMID 39739618, 2025). "Thus, although the critical role of CDC6 in paclitaxel resistance has been firmly established, identifying compounds that selectively target tumor cells to reduce CDC6 protein levels represents a promising therapeutic strategy." (PMID 41339304, 2025). "Therefore, the relationship between SKCM and the tumor immune microenvironment of CDC6 needs further exploration in future research." (PMID 39052109, 2024). "The decrease in tumour growth coincided with a reduction in the protein levels of Ki-67 and CDC6." (PMID 38685067, 2024). "Indeed, some studies have shown that neoplastic tumor growths often exhibit an increased expression of replication licensing factor CDC6, responsible for the loading of MCM proteins onto replication origins." (PMID 39184446, 2024). "However, its known role in tumor development and prognosis has made CDC6 a focal point of our study." (PMID 39052109, 2024). "Moreover, ectopic expression of CDC6 effectively reversed the OTUD6A knockdown-mediated tumour growth inhibition in vivo." (PMID 38685067, 2024). "Interestingly, we observed no significant variation in the promoter methylation level of CDC6 between normal tissues and primary tumor tissues." (PMID 37945594, 2023). "This correlation of CDC6 with tumor cell proliferation was similarly observed in our experiments." (PMID 37342242, 2023). "In total, 193 cells expressed CDC6, of which 107 were tumor cells and 86 were normal cells." (PMID 37945594, 2023). "Moreover, Nutlin also regulated the tumor-promoting HSF1 targets CDC6, ITGB3BP, RBBP5, BST2, and FBLN1." (PMID 34188043, 2021). "The Pairwise boxplot also showed that most tumor samples had high expression of CDC6 (P <0.001)." (PMID 34136398, 2021). "In the HPA data, compared with normal tissues, the expression of PKMYT1, ETF1, RECQL4, TUBB2B, and CDC6 in tumor tissues was remarkably upregulated, while the expression of TFRC and PITX1 was significantly downregulated (,ECT2, BUBB1B, and COCH were not included)." (PMID 33869220, 2021). "CDC6 expression of in tumor tissues was higher than that in normal tissues (P <0.001)." (PMID 34136398, 2021). "The results of IHC staining showed that among the 118 cases(including 114 tumor cases and four normal cases), 56 cases had high expression of CDC6 levels, 58 cases had low CDC6 expression levels and four cases had negative results(all the negative results are from the normal cases)." (PMID 34136398, 2021). "Importantly, we found that expression of TCF4, CDC2 and CDC6 is up‐regulated in HCC tumour compared with non‐tumour tissue from GSE 37367, including over 400 human HCC samples." (PMID 33951279, 2021). "Furthermore, the results of the corresponding clinical data showed that CDC6 expression is closely related to age, tumor size, T stage and Fuhrman grade." (PMID 34136398, 2021).